SPARC (secreted protein acidic and cysteine rich)
Diseases named in the same sentence as SPARC in open-access papers (continued):
Sharing a sentence is not in itself a finding about the gene and the disease.
cancer (continued). "Mechanistically, we demonstrate that miR-29a and C4A act synergistically through SPARC down-modulation promoting cancer cell colonization." (PMID 42129855, 2026). "SPARC knockdown in CRC cells significantly suppressed aerobic glycolysis and 5‐FU resistance, whereas SPARC overexpression had cancer‐promoting effects." (PMID 40415238, 2025). "Key oncogenes, including SERPINE1, MMP13, INHBA, and SPARC, emerged as central to these effects, consistent with their reported contributions to cancer progression across various malignancies." (PMID 40361356, 2025). "Four genes (CDH13, CYB5R2, RARB2 and SPARC) showed the expected significant hypermethylation (p < 0.05) in cancer patients compared with HDs, whereas DRD2 and LINE-1 were hypomethylated (p < 0.05), as anticipated." (PMID 41008642, 2025). "CLDN1, EphB4, LAT1, FOXM1, HSP105α, ROBO1, and SPARC were identified as potential targets for common cancer antigens for primary CRC." (PMID 40806530, 2025). "Several studies have demonstrated that albumin nanoparticle internalization in HEK293 cells occurs via a SPARC-dependent pathway, with uptake levels comparable to those observed in cancer cells (~75% as measured by confocal microscopy and flow cytometry)." (PMID 41373713, 2025). "Increasing evidence has shown that SPARC is expressed at elevated levels in a variety of cancers, such as mesothelioma, haematological malignancies, osteosarcoma, and gastric carcinomas, and this phenotype is associated with a poor prognosis." (PMID 40415238, 2025). "The upregulation of SPARC in OSCC suggests its involvement in the transformative alterations of the epithelium as well as its potential as an early event in the process of cancer development." (PMID 39865173, 2025). "Several reports have suggested the role of SPARC in contributing towards a pro-invasive phenotype in cells of multiple cancer types." (PMID 40810390, 2025). "The downregulation of SPARC expression via DNA methylation is commonly observed in chronic inflammation and cancer." (PMID 40702315, 2025). "Both FOXM1 and SPARC, almost undetectable in normal liver tissues, facilitate cancer cell migration and invasion in CRC." (PMID 40806530, 2025). "Several other extracellular stroma-associated proteins specifically linked to CTSK, including SPARC and TNC, are reportedly highly expressed in cancer tissue and promote the invasion and metastasis of multiple cancers." (PMID 38594611, 2024). "The relevant CAF-associated genes (CAFG)(representing R index = 0.9 or beyond with SPARC) were selected based on stroma specificity (cancer stroma/epithelia, cS/E = 10 or beyond) and expression amounts, which were largely exhibited negative prognostic impacts." (PMID 38557819, 2024). "Genes MAGI2-AS3, MALAT1, and SPARC were identified as having a differential impact on the metastatic and invasive capabilities of cancer cells." (PMID 39336798, 2024). "These collective findings bolster the idea of targeting SPARC therapeutically in various malignancies, and a deeper exploration into the molecular mechanisms that regulate SPARC expression in cancers is imperative." (PMID 38650694, 2024). "Future studies should focus on further validating exercise-responsive biomarkers like OSM, SPARC, miRNA-1, and miRNA-133a, which have demonstrated relevance in cancer biology." (PMID 39766184, 2024). "Secreted protein acidic and rich in cysteine (SPARC) has been shown to modulate aggressive behavior in several benign and malignant tumors." (PMID 38347494, 2024). "Understanding the mechanisms that govern SPARC expression in cancers has the potential to lead to improved cancer diagnosis, prognosis, treatment strategies, and patient outcomes." (PMID 38650694, 2024). "This pattern of SPARC expression has been reported in several cancers such as lung, breast, colorectal and oral cancers." (PMID 38347494, 2024).
cancer (continued). "In 2008, a review by Tai and Tang introduced in detail the role of SPARC in cancer progression and its potential for cancer therapy, and the role of SPARC in sensitizing therapy-resistant cancer types was also discussed." (PMID 38323081, 2024). "Having uncovered HDAC10’s regulation in SPARC expression, we sought to explore its biological implications in cancer cells." (PMID 38650694, 2024). "Although some glycoproteins increase the stemness of several cancer cell types, SPARC glycoprotein was shown to have a cell type-specific role in regulating the stemness of different cancer types." (PMID 38562556, 2024). "In particular, diverse MCPs such as CCN family proteins, THBS, and SPARC have emerged as independent prognostic markers for unfavorable cancer outcomes." (PMID 38946720, 2024). "Further, by interactions with soluble factors and consequent alteration in signaling pathways, SPARC impacts proliferation and migration in cancer cells." (PMID 38650694, 2024). "The genes COL1A2, FSTL1, LUM, and SPARC encode proteins that structurally compose the ECM and that are frequently altered in cancer, conferring a poor prognosis and invasive phenotypes." (PMID 39563861, 2024). "The role of SPARC in cancer has generated considerable interest owing to the fact that it functions not only its ability to modulate cell-cell and cell–matrix interactions, but its de-adhesive and growth inhibitory properties in non-transformed cells." (PMID 39424639, 2024). "Depending on the specific cell types and animal models under study, SPARC can manifest contrasting roles in cancer." (PMID 38650694, 2024). "They found that SPARC-derived fibroblasts promoted migration velocity and depth of invasion of these cancer cells." (PMID 38347494, 2024). "Co‐labeling with anti‐SPARC and anti‐periostin antibodies showed that SPARC (in green) partially co‐localized with periostin (in red) in CAFs at the cancer cell‐stromal interface." (PMID 36346290, 2023). "Some in vitro studies in which SPARC was overexpressed or silenced in cancer cells showed its inhibitory effect on cancer cell motility, invasion and proliferation." (PMID 36346290, 2023). "It has been reported that SPARC regulates signaling pathways that influence epithelial‐to‐mesenchymal transition, cell adhesion, motility and invasiveness of cancer cells." (PMID 36346290, 2023). "Considerable evidence has shown that SPARC mediates the TGF-β1 signaling pathway in different cancer types." (PMID 37509139, 2023). "As the sixth most common cancer worldwide, the overexpression of SPARC reduces HCC proliferation during spheroid cell culture." (PMID 37577749, 2023). "In papillary thyroid cancer (PTC), MCM3AP-AS1 was reported to promote proliferation and invasion of cancer cells through regulating the miR-211-5p/SPARC axis." (PMID 35929906, 2023). "Clinical cancer samples confirmed that SPARC can be a candidate therapeutic marker and prognostic indicator for the diagnosis of NSCLC." (PMID 37577749, 2023). "Another study on the paracrine effects of tumor-derived factors revealed that SPARC overexpression in cancer cells decreased macrophage and mesothelial production of IL-6, MMPs, urokinase plasminogen activator, prostaglandin E2, and 8-isoprostanes." (PMID 37545408, 2023). "Secreted protein acidic and cysteine-rich (SPARC) also plays a key role in cancer through extracellular matrix remodeling and promoting epithelial-mesenchymal transition." (PMID 37868053, 2023). "SPARC is a matricellular protein that participates in the activation of the epithelium–mesenchyme transition through the AKT pathway in some types of cancer." (PMID 38137452, 2023). "SPARC modulates TGF-β1 fibrillar ECM deposition through a novel mechanism to influence cancer cell biology." (PMID 37577749, 2023). "As a candidate therapeutic approach for tumors, future research can focus on the highly expressed sites of SPARC in cancer cells." (PMID 37577749, 2023).
cancer (continued). "As many tumors express high levels of BSA-binding proteins (e.g., SPARC), it is often loaded with Polymer Materials as an anti-cancer targeted drug delivery system." (PMID 37062822, 2023). "It has been demonstrated that SPARC promotes intratumoral aggregation of albumin-bound nanoparticles, and nab-paclitaxel utilizes this characteristic of cancer biology, as it is preferentially retained by tumoral SPARC." (PMID 37509639, 2023). "SPARC has been studied in cancer and bone biology for a long time; indeed, SPARC affects the prognosis of some types of cancers and bone tissue development and maintenance, as determined by discovery of mutations and mouse-model studies." (PMID 37781916, 2023). "Previous research studies have indicated the potential mechanisms behind the therapeutic benefits resulting from the interaction between HSA and SPARC, a protein that is overexpressed in cancer cells." (PMID 37836018, 2023). "Here, we summarize the omics advances of the SPARC gene, including the summary of SPARC gene expression associated with prognosis in pancancer and MESO, the immunosuppressive microenvironment, and cancer cell stemness." (PMID 37509139, 2023). "The expression level of SPARC was confirmed by real-time PCR and Western blot analysis in various cancer cell lines." (PMID 36614294, 2023). "Genes normally repressed by EWS::FLI1 but upregulated in EWS::FLI1 "low states", including LOX, TGF-beta, FN1, SPARC, and NT5E, have been implicated in MDSC recruitment or activity in other cancers." (PMID 36505823, 2022). "Research has indicated that SPARC is related to some cancers' metastatic potential, including prostate cancer, cervical carcinoma, and BC." (PMID 36157225, 2022). "Examples of SPARC counteracting inflammation and cancer would be two illustrations of such “regulatory feedback”." (PMID 35741776, 2022). "SPARC is secreted into the extracellular matrix from cancer and stromal cells, and high SPARC-mRNA expression is related to metastasis and poor prognosis in several types of cancers." (PMID 35260632, 2022). "Functioning as an extracellular protein, SPARC has essential functions in cancer cell proliferation, migration, angiogenesis, matrix cell adhesion, and tissue remodeling." (PMID 35477379, 2022). "Ma0 cluster was populated in PT and highly expressed VEGFA and SPARC, which are essential macrophage genes that induce angiogenesis and cancer cell migration." (PMID 35184420, 2022). "The expression of SPARC is strictly regulated in normal cells, whereas it is excessively present on cancer membranes." (PMID 35456562, 2022). "Numerous studies have confirmed that SPARC affects cancer progression by modulating cell adhesion, invasion, metastasis, and angiogenesis." (PMID 35912006, 2022). "There is a compilation of studies on the effects of different levels of SPARC expression in tumors and neighboring cells where in some cases SPARC is deleterious and in other types of cancer, it inhibits proliferation and metastasis." (PMID 36430810, 2022). "SPARC expression can be employed as a good marker for the prognosis of patients with cancers, which will provide new methods and ideas for preventive treatment." (PMID 35211625, 2022). "SPARC plays a crucial role in the development of many diseases, including cancer and cardiovascular, osteoarticular, and metabolic diseases." (PMID 35721704, 2022). "On the other hand, several integrins have been described as mediators of some of the SPARC effects on cancer cells." (PMID 35682554, 2022). "Further analysis of the correlation between these key genes and the pathological stage of GC showed that COL1A1, COL5A2, P4HA3, and SPARC were significantly correlated to cancer pathological stages." (PMID 35368700, 2022). "The relationship between SPARC expression and cancer invasion was highlighted in super-resolution, whereas detecting the invasive region using original spatial transcriptome data was difficult because the measured spots were not dense." (PMID 35260632, 2022).
cancer (continued). "Further, it has been known SPARC overexpression inhibits cancer cell proliferations, thus making it a potential target for cancer detection and treatment." (PMID 36157225, 2022). "Similar to VIM, although SPARC was remarkably overexpressed in most cancer types, a ten-fold increased expression seen in GBM makes it crucial;;." (PMID 35571016, 2022). "In contrast to the EPR effect, SPARC-related spontaneous uptake by cancer cells occurs selectively for the albumin." (PMID 35456562, 2022). "SPARC is attracting increasing interest as a potential prognostic biomarker in patients with cancer." (PMID 35981080, 2022). "Other upregulated genes (e.g., THBS3, SPARC, and SPP1) have also been implicated in cancer cell invasiveness." (PMID 35205840, 2022). "SPARC plays multiple contextual functions depending on the cancer type and stage, and its precise role(s) in TNBC remains to be studied." (PMID 33995652, 2021). "Conversely, SPARC was expressed mainly in fibroblasts, macrophages and endothelial cells, whereas its expression level in cancer cells was variable." (PMID 33995652, 2021). "Taken together, these results indicated a critical role of interaction with the extracellular matrix in SPARC-promoting cancer cell proliferation." (PMID 34912848, 2021). "One kind of 60-kDa sialoglycoprotein (gp60) and secreted protein acidic and rich in cysteine (SPARC), an albumin receptor, are highly expressed on the surface of endothelial cells and cancer cells, respectively." (PMID 33855017, 2021). "The function of SPARC in cancer cells is somewhat controversial and its impact on peritumoral stromal cells remains to be resolved." (PMID 33579227, 2021). "In various kinds of cancer, strong SPARC expression was observed in stromal cells in contrast with its low expression in cancer epithelial cells." (PMID 33579227, 2021). "The expressions of BGN, COMP, COL5A2, and SPARC were further verified using scRNA-seq data between cancer and normal samples." (PMID 34899080, 2021). "Function enrichment analysis of SPARC-correlated genes indicated a critical role of interaction with an extracellular matrix in SPARC-promoting cancer cell proliferation." (PMID 34912848, 2021). "These women are recommended to first respond to a questionnaire and provide information such as age, family history of cancer, etc., and then undergo gynecologic ultrasonography and proteomic analysis of SPARC and THBS1." (PMID 34064977, 2021). "In various kinds of cancer, strong SPARC expression was observed in stromal tissues as well as in cancer epithelial cells." (PMID 33579227, 2021). "Plus, nab-paclitaxel has exhibited clinical antitumour activity in several cancer types that overexpressed SPARC." (PMID 34336679, 2021). "The region of cancer tissue positive for SPARC also showed FN1 expression in the stromal area, and the region without SPARC expression also lacked FN1 expression the stromal area." (PMID 33579227, 2021). "Immunohistochemical analysis of EC specimens showed that SPARC expression level was stronger in the cancer cells compared with the stromal area." (PMID 33579227, 2021). "Unlike CA-125, which increases the quantitative value in the blood when cancer occurs, SPARC shows low variation between different genetic backgrounds and is highly expressed upon OC onset." (PMID 34064977, 2021). "There were 613 SPARC-expressing cells, of which only 73 were from normal tissues and 540 were from cancer tissues." (PMID 34899080, 2021). "We observed enhanced proliferation of NF co-cultured with the SPARC-expressing cancer cells in vitro." (PMID 33579227, 2021). "SPARC is a well-known ECM protein gene and it has also been reported that the SPARC protein increases cancer cell invasiveness and migration." (PMID 34638346, 2021). "Analysis of FN1 expression in the sequential sections showed that SPARC expression in cancer cells was adjacent to FN1 expression in the surrounding stromal tissue." (PMID 33579227, 2021).
cancer (continued). "SPARC is also correlated with increased cancer metastasis and its increased expression in cancer stromal cells results in epithelial-to-mesenchymal transition by downregulation of E-cadherin and upregulation of N-cadherin." (PMID 33904394, 2021). "Nab-Paclitaxel, a 130 nm albumin-bound formulation of paclitaxel particles, was shown to exert antitumor activity in various cancers that overexpress SPARC, including breast cancer, lung cancer, and melanoma." (PMID 33466303, 2021). "Both SPARC mRNA and protein have been observed in cancer and stromal cells of ESCC, and overexpression of SPARC was significantly associated with metastasis and poor prognosis 14-16." (PMID 31897236, 2020). "SPARC can act as both an inhibitor and promoter in cancer; the real effect of SPARC can be altered by other genes owing to its epistatic effects." (PMID 32848739, 2020). "Herein, the high biocompatibility and hemocompatibility properties of the HSA-modified NPs are reported along with the very strong increase in signal stability and the efficient and specific uptake by a cancer cell line via a SPARC-mediated mechanism." (PMID 32733871, 2020). "Moreover, SPARC regulates the activity of several growth factors such as platelet-derived growth factor, basic fibroblast growth factor and vascular endothelial growth factor that can all play a pivotal role in platelet molecular mechanisms underlying cancer progression and metastases." (PMID 33383671, 2020). "Remarkably, correlation analyses revealed a negative regulation on SPARC transcription by isomiRs involved in cancer signaling, suggesting a specific ”education” in PDAC platelets." (PMID 33383671, 2020). "It has recently been reported that exercise-induced SPARC expression suppresses cancer, as azoxymethane (AOM)-induced colonic tumorigenesis is inhibited by exercise, but not in SPARC(-/-) mice." (PMID 33019579, 2020). "The secreted protein acidic and rich in cysteine (SPARC) is a multi-faceted protein that has a well-documented function in the malignant features of various types of cancer." (PMID 32117645, 2020). "Subsequently, this study further explored the role of SPARC derived from macrophages in M2-mediated cancer malignant phenotypes." (PMID 32226513, 2020). "Each osteomimetic marker harbored prognostic value in the pan-cancer analyses [SPARC: hazard ratio (HR) = 1.10, p = 0.028; SPP1: HR = 1.25, p < 0.001; BGLAP: HR = 1.13, p = 0.005]." (PMID 33240930, 2020). "It belongs to the secreted protein acid and rich in cysteine (SPARC) family and it exhibits variable expression during pathological conditions including cancer." (PMID 32050622, 2020). "Increased expression of SPARC has been found to play a protumorigenic and prometastatic role to many malignant tumours, such as brain, lung, breast, pancreas, skin, and kidney." (PMID 31186631, 2019). "SPARC (secreted protein acidic and rich in cysteine) is defined as an albumin-binding glycoprotein that is frequently over-expressed in cancer cells." (PMID 31783552, 2019). "SPARC can enhance cell invasion, metastasis, and growth while inducing apoptosis in gastric and ovarian cancers." (PMID 30886783, 2019). "Here, we showed alterations in cancer cell invasion based on SPARC levels of fibroblasts in 3D co-culture." (PMID 31554208, 2019). "Dr. Kratz reported that albuminemia is probably (together with Gp60 and SPARC) one of the targeting mechanisms at the base of the Abraxane success, as cancer cells can avidly consume this protein." (PMID 31195727, 2019). "Gp60 and secreted protein acidic and rich in cysteine (SPARC) receptors are the most important because they were shown to be involved in the transport of ANVs in cancer diseases." (PMID 31195727, 2019). "Since rSPARC deposited in a Collagen I matrix increased the mobility of cancer cells, we wanted to investigate the effects of fibroblast derived SPARC on cancer cell motility in a more complex system." (PMID 31554208, 2019).